DCAF12 (DDB1 and CUL4 associated factor 12)
Description:
Substrate-recognition component of a DCX (DDB1-CUL4-X-box) E3 ubiquitin-protein ligase complex of the DesCEND (destruction via C-end degrons) pathway, which recognizes a C-degron located at the extreme C terminus of target proteins, leading to their ubiquitination and degradation. The C-degron recognized by the DesCEND pathway is usually a motif of less than ten residues and can be present in full-length proteins, truncated proteins or proteolytically cleaved forms. The DCX(DCAF12) complex specifically recognizes proteins with a diglutamate (Glu-Glu) at the C-terminus, such as MAGEA3, MAGEA6 and CCT5, leading to their ubiquitination and degradation. Ubiquitination of MAGEA3, MAGEA6 by DCX(DCAF12) complex is required for starvation-induced autophagy. Also directly recognizes the C-terminal glutamate-leucine (Glu-Leu) degron as an alternative degron in proteins such as MOV10, leading to their ubiquitination and degradation. Controls the protein level of MOV10 during spermatogenesis and in T cells, especially after their activation.
Synonyms: KIAA1892; TCC52; WDR40A; DKFZP434O125; MGC1058; CT102
Tractability: PROTAC: ubiquitination databases record sites on it.
Gene: Protein-coding gene on chromosome 9 (34,086,384 to 34,127,399, reverse strand). Ensembl gene ENSG00000198876.
Subcellular location: Cytoplasm; Cytoplasm, cytoskeleton, microtubule organizing center, centrosome; Nucleus
Gene Ontology:
Molecular function: protein binding; ubiquitin-like ligase-substrate adaptor activity
Biological process: regulation of autophagy; T cell activation; ubiquitin-dependent protein catabolic process via the C-end degron rule pathway; regulation of cell population proliferation; regulation of miRNA-mediated gene silencing; protein ubiquitination
Cellular component: centrosome; Cul4-RING E3 ubiquitin ligase complex; cytoplasm; cytosol; nucleus; Cul4A-RING E3 ubiquitin ligase complex; Cul4B-RING E3 ubiquitin ligase complex
Genetic constraint (gnomAD): Loss-of-function variants: 28 observed, 54.97 expected, observed/expected ratio (o/e) 0.51, 90% interval 0.38 to 0.7. The upper end of that interval is the gene's LOEUF score, 0.7, which puts it in group 2 of 6, group 1 being the genes least tolerant of losing a copy. Missense variants: 425 observed, 574.1 expected, observed/expected ratio (o/e) 0.74, 90% interval 0.68 to 0.8. Synonymous variants: 196 observed, 226.62 expected, observed/expected ratio (o/e) 0.86, 90% interval 0.77 to 0.97.
Homologues: Orthologues: chimpanzee DCAF12 (99% identical), pig DCAF12 (99% identical), mouse Dcaf12 (98% identical), rat Dcaf12 (98% identical), rabbit DCAF12 (97% identical), macaque DCAF12 (96% identical), dog DCAF12 (94% identical), tropical clawed frog dcaf12 (78% identical), zebrafish dcaf12 (76% identical), guinea pig DCAF12 (72% identical). Paralogues in human: DCAF12L2 (65% identical), DCAF12L1 (62% identical).
Diseases named in the same sentence as DCAF12 in open-access papers:
DCAF12 is named in the same sentence as 11 diseases in open-access papers, as found by Europe PMC text mining. Sharing a sentence is not in itself a finding about the gene and the disease. The quoted sentences say what the papers report.
autism (1 paper, 2022). Persistent deficits in social interaction and communication and interaction as well as a markedly restricted repertoire of activity and interest as well as repetitive patterns of behavior. "DCAF12 and PSMC4 are both involved in the degradation of ubiquitinated proteins, but there have been no studies showing a relation between these two genes and autism." (PMID 36761165, 2022).
hepatitis B (1 paper, 2022). "Transcriptome analysis of blood before and after hepatitis B vaccination showed that the level of DCAF12 in nonresponders was significantly upregulated after immunization." (PMID 35655486, 2022).
lung adenocarcinoma (1 paper, 2026). A carcinoma that arises from the lung and is characterized by the presence of malignant glandular epithelial cells. "Combined, these results established that DCAF12 drives lung adenocarcinoma metastasis mediated by CRL4‐mediated ubiquitination." (PMID 41047465, 2026). "Analysis of The Cancer Genome Atlas (TCGA) data revealed that seven DCAF genes (DCAF2, DCAF4, DCAF7, DCAF12, DCAF13, DCAF15, and DCAF17) were significantly upregulated in lung adenocarcinoma (LUAD)." (PMID 41047465, 2026).
lung carcinoma (1 paper, 2026). "This conserved function was further demonstrated in human lung cancer lines (A549 and H1299), where DCAF12 silencing significantly reduced motility in Transwell and wound healing assays." (PMID 41047465, 2026). "Together, these results confirm that DCAF12 promotes lung cancer metastasis through ubiquitination‐dependent regulation of TRiC/CCT subunits." (PMID 41047465, 2026). "Our study identified DCAF12 as a central signaling integrator in lung cancer metastasis, bridging cytoskeletal dynamics with oncogenic pathways through its regulation of the TRiC/CCT chaperonin complex." (PMID 41047465, 2026). "In conclusion, our study establishes DCAF12 as a primary regulator of lung cancer metastasis through a dual mechanism: stabilizing the TRiC/CCT complex via non‐degradative ubiquitination to maintain cytoskeletal dynamics, and concurrently activating the YAP, STAT3, and mTOR pathways." (PMID 41047465, 2026). "Using this multifaceted approach, we established that DCAF12 is a physiological interactor of the TRiC/CCT complex, implicating its potential role in modulating TRiC/CCT function during lung cancer progression." (PMID 41047465, 2026).
metastatic tumors (1 paper, 2026). "By bridging chaperone‐mediated protein folding with oncogenic signaling, this study redefines DCAF12 as a central orchestrator of metastasis through ubiquitin‐dependent chaperone regulation, revealing new therapeutic opportunities for targeting metastatic disease." (PMID 41047465, 2026). "Notably, metastatic tumors (n = 24) exhibited higher DCAF12 levels than non‐metastatic tumors (n = 66; p = 0.028)." (PMID 41047465, 2026).
thyroid cancer (1 paper, 2020). "This indicates the diagnostic potential of DCAF12 and miR-222 joint expression evaluation in thyroid cancer." (PMID 32899424, 2020). "DCAF12 is mostly upregulated in various cancers tissues compared to normal ones and only in the adrenal gland, bone, testis and thyroid cancers it is downregulated." (PMID 32899424, 2020).
cancer (6 papers, 2020 to 2026). A tumor composed of atypical neoplastic, often pleomorphic cells that invade other tissues. "The evolutionary repurposing of the molecular function of DCAF12, from apoptosis regulation in Drosophila to ubiquitin‐dependent metastasis promotion in humans, prompted us to investigate its cancer‐specific mechanism." (PMID 41047465, 2026). "This convergence of evidence confirms the central role of DCAF12‐mediated TRiC/CCT regulation in cancer progression and offers multiple potential avenues for clinical intervention." (PMID 41047465, 2026). "Considering the established connection between cancer stemness and metastasis, we investigated the role of DCAF12 in tumorsphere formation." (PMID 41047465, 2026). "In cancer cells, DCAF12 targets MAGE-A3 and MAGE-A6 for degradation in response to starvation." (PMID 34065512, 2021). "DCAF12 is mainly nuclear in human cancer cells, while MOV10 is dominantly cytoplasmic." (PMID 34065512, 2021). "Next, we investigated whether DCAF12 mediates MOV10 degradation in cancer cells." (PMID 34065512, 2021). "Notably, unlike its role in Drosophila, this cancer‐specific activity is fundamentally dependent on the ubiquitin ligase activity of DCAF12." (PMID 41047465, 2026). "Endogenous CCT5 protein levels were previously shown to increase upon DCAF12 knockout in the A-375 cancer cell line, but the interaction could not be confirmed in our analysis using HEK293T cells." (PMID 38665159, 2024). "The different subcellular localization of DCAF12 and MOV10 in human cancer cells might explain why we could not reliably observe an increased MOV10 protein level and stability after DCAF12 depletion using small inhibitory (si) RNA or in DCAF12 KO HCT116 cells (data not shown)." (PMID 34065512, 2021).
tumor (2 papers, 2025 to 2026). "DCAF12 depletion suppresses tumor cell migration and stemness in vitro and reduces pulmonary/hepatic metastasis in vivo." (PMID 41047465, 2026). "Our study uncovered a striking, context‐dependent functional switch for DCAF12, which exhibits oncogenic activity in mammals despite its tumor‐suppressive role in Drosophila, highlighting the therapeutic potential of targeting the DCAF12‐TRiC/CCT axis." (PMID 41047465, 2026). "Further validation in an independent cohort of 90 LUAD patients with survival data confirmed elevated DCAF12 expression in tumor tissues compared to that in adjacent non‐tumor tissues (p < 0.0001), which was consistent with the findings from the public CPTAC dataset." (PMID 41047465, 2026).
intestinal fistula (1 paper, 2017). "DCAF12 (rs10758242) and TGFBR3 (rs284148) showed modest associations with intestinal fistula development and intestinal stricture, respectively." (PMID 28045058, 2017).
DCAF12 also shares sentences with these, for which no sentence is quoted: myasthenia gravis (1 paper); neurodegenerative disease (1).